BCL2 (BCL2 apoptosis regulator)
Diseases named in the same sentence as BCL2 in open-access papers (continued):
Sharing a sentence is not in itself a finding about the gene and the disease.
medulloblastoma (32 papers, 2009 to 2025). A malignant, invasive embryonal neoplasm arising from the cerebellum. "Our data suggest that regulation of BCL2 by miRNA-10b is associated with proliferation and survival of medulloblastoma cells." (PMID 26394044, 2015). "Potential therapeutic benefits of statin therapy in medulloblastoma were reported to be associated with Bcl2 and apoptosis." (PMID 22887866, 2012). "To validate this, we compared BCL2 expression in normal cerebellum and different datasets of medulloblastoma in the R2 database." (PMID 41301024, 2025). "To further support the role of BCL2 in mediating medulloblastoma aggressiveness and its potential as a therapeutic target, we employed a genetic approach to downregulate BCL2 using siRNA." (PMID 41301024, 2025). "Venetoclax showed significant specificity in medulloblastoma model cell lines, further supporting its potential relevance considering that BCL2 expression correlated to the most aggressive form of medulloblastoma." (PMID 41301024, 2025). "This analysis reveals a global upregulation of BCL2 across several datasets of medulloblastoma compared to healthy cerebellum." (PMID 41301024, 2025). "Our findings add to these data by demonstrating the impact of OTX2-AS1 expression on the response of cultured medulloblastoma cells to pharmacological BCL-2 inhibition." (PMID 37976029, 2023). "In this respect, we performed comparative high-throughput drug screening on medulloblastoma cells and identified two BCL-2 inhibitors (ABT-737 and Navitoclax) that specifically reduced cell viability of medulloblastoma cells with high OTX2-AS1 expression." (PMID 37976029, 2023). "Collating PCA and DR_MOMP findings suggested that the BCL-2 proteins play a key role in mediating cisplatin sensitivity in medulloblastoma cells." (PMID 37898609, 2023). "BCL-2 is frequently overexpressed in medulloblastoma, and several studies focused on the growth-inhibitory effect of BCL-2 inhibition." (PMID 37976029, 2023). "Pharmacological inhibition of BCL-2 suppressed the growth of OTX2-AS1 overexpressing medulloblastoma cells in vitro." (PMID 37976029, 2023). "Our study revealed a pro-tumorigenic role of OTX2-AS1 in medulloblastoma and identified BCL-2 inhibition as a potential therapeutic approach to target OTX2-AS1 overexpressing medulloblastoma cells." (PMID 37976029, 2023). "Together with current efforts to improve the tolerability and cancer-specificity of BCL-2 targeting drugs, these novel treatment strategies have the potential to significantly improve the clinical management of medulloblastoma patients." (PMID 37898609, 2023). "BCL-XL is the most frequently expressed anti-apoptotic BCL-2 protein in medulloblastoma tumours and is expressed in the majority of medulloblastoma cell lines." (PMID 35568716, 2022). "BCL-2 has also been identified as an important mediator of Hedgehog activity in the Sonic Hedgehog (SHH) subtype, and Gli1 and Gli2, essential transcriptional drivers of the SHH subtype of medulloblastoma, regulate BCL-2 transcription." (PMID 35568716, 2022). "The knockdown of lncRNA CRNDE induces apoptosis via promoting the activity of caspase-3 in medulloblastoma cells Cleaved-caspase-3, caspase-9, and Bax elevation, and bcl-2 reduction are the results of HOTAIR downregulation in medulloblastoma cells." (PMID 35111757, 2021). "SHH medulloblastoma models were also developed by overexpressing Shh, alone or in combination with mycn or bcl2 with the RACS-TVA system." (PMID 33869004, 2021). "sicircSKA3 reduces Bcl-2, while elevates caspase-3 in medulloblastoma cells by targeting miR-383-5p." (PMID 35111757, 2021).
medulloblastoma (continued). "Several studies have evaluated the effect of miR-10b on the growth and proliferation of medulloblastoma through the transcriptional induction of BCL-2, a tumour promoter." (PMID 34944941, 2021). "Several studies suggest that miR-10b is an oncomiR that regulates cell growth and survival of this medulloblastoma subgroup by controlling BCL2 levels." (PMID 34944941, 2021). "Several other studies also demonstrated that Bcl-2 expression was enhanced by ERβ in cardiomyocytes, medulloblastoma cells and BCa cells." (PMID 31076571, 2019). "To further elucidate simvastatin-induced cell death in medulloblastoma cells, we investigated the expression of anti- and pro-apoptotic proteins in the Bcl-2 family [Mcl-1, Bcl-xl, Bcl-2 (anti-apoptotic) and Bax (pro-apoptotic) at 24 h, 48 h, and 72 h]." (PMID 31319483, 2019). "While simvastatin induced significant cell death in all three medulloblastoma cell lines, there were variations in the expression of Bcl-2 pro- and anti-apoptotic proteins after simvastatin treatment." (PMID 31319483, 2019). "Inhibition of miRNA-10b abrogated the colony-forming capability of medulloblastoma cells, and markedly down-regulated the expression of BCL2." (PMID 26394044, 2015). "ABT-737, a BCL2 antagonist, has been shown to inhibit proliferation and induce apoptosis in medulloblastoma cells at 10 μM." (PMID 26394044, 2015). "This study demonstrates the effect of miRNA-10b on medulloblastoma growth and proliferation through transcriptional induction of BCL2, a cellular proto-oncogene and tumor promoter." (PMID 26394044, 2015). "To further define the role BCL2 plays in apoptosis induced by miRNA-10b inhibition, we inhibited BCL2 expression in medulloblastoma cells, which resulted in significant downregulation of miRNA-10b expression." (PMID 26394044, 2015). "In contrast, inhibition of miRNA-10b by anti-miRNA10b resulted in decreased BCL2 expression, and was accompanied by increased sensitivity of medulloblastoma cells to apoptosis." (PMID 26394044, 2015). "We found that overexpression of miRNA-10b significantly induced the expression of BCL2 in both the DAOY and UW228 cell lines, suggesting that miRNA-10b positively regulates BCL2 in medulloblastoma cells." (PMID 26394044, 2015). "We demonstrate that high levels of miRNA-10b increase medulloblastoma proliferation by directly or indirectly regulating BCL2 levels, thereby controlling apoptosis." (PMID 26394044, 2015). "Collectively, our data demonstrate that BCL2 is an important mediator of the effects of miRNA-10b in medulloblastoma, and suggest a potential new therapeutic approach in the treatment of medulloblastoma." (PMID 26394044, 2015). "Our data provide strong evidence that miRNA-10b regulates BCL2 expression, and thus induces the proliferation of medulloblastoma cells." (PMID 26394044, 2015). "This study suggests that BCL2 is an important mediator of miRNA-10b activity in medulloblastoma, and suggests a new therapeutic target." (PMID 26394044, 2015). "This study demonstrates that miRNA -10b regulates the proliferation and survival of medulloblastoma cells by targeting BCL2." (PMID 26394044, 2015). "This study demonstrates the effects of miRNA-10b on medulloblastoma proliferation through transcriptional induction of the anti-apoptotic protein BCL2." (PMID 26394044, 2015). "Our preliminary studies indicated that miRNA-10b is an oncomir regulating the growth and survival of medulloblastoma cells by controlling the levels of BCL2." (PMID 26394044, 2015). "Our further investigation showed that downregulation of uPAR and MMP-9 inhibited the transcriptional activity of STAT3 in regulating the expression of Bcl-2 and survivin in medulloblastoma." (PMID 22984561, 2012). "Results from our studies suggest that apoptotic stimuli generated by downregulation of uPAR and MMP-9 counteract the function of anti-apoptotic Bcl-2 and Bcl-xL molecules and activate pro-apoptotic Bak in medulloblastoma cells." (PMID 22984561, 2012).
medulloblastoma (continued). "In medulloblastoma cells, increased expression of the Hh signaling target positively regulated Bcl-2 transcription, whereas pharmacological suppression of Hh activity resulted in decreased Bcl-2 expression and increased apoptosis." (PMID 19742123, 2009). "Our results thus suggest that activation of the cell death machinery by pharmacological inhibition of BCL-2 could be a promising approach in medulloblastoma cells with high OTX2-AS1 expression." (PMID 37976029, 2023). "Indeed, mouse studies have shown that postnatal overexpression of BCL-2 promotes medulloblastoma tumour formation in cooperation with Sonic hedgehog pathway activation, highlighting a subtype-specific role for BCL-2 in medulloblastoma." (PMID 35568716, 2022). "Interestingly, in medulloblastoma BCL-2 is the least frequently expressed of the anti-apoptotic BCL-2 proteins, although expression is associated with poorly differentiated and highly proliferative tumour regions, and tends to correlate with poor outcome." (PMID 35568716, 2022). "In medulloblastoma samples, Gli-1 expression was clearly correlated with Bcl-2 mRNA levels." (PMID 26716648, 2016). "The mechanistic steps between miRNA-10b and BCL2 in medulloblastoma have yet to be elucidated." (PMID 26394044, 2015). "It was hypothesized that potent inhibitors of BCL2, known for their antiproliferative and apoptotic effects on medulloblastoma cells, inhibit the expression of miRNA-10b." (PMID 26394044, 2015). "It was hypothesized that downregulation of BCL2 would downregulate miRNA-10b, and thus induce apoptosis and growth inhibition in medulloblastoma cells." (PMID 26394044, 2015). "The data presented here indicate that miRNA-10b may act as an oncomir in medulloblastoma tumorigenesis, and reveal a previously unreported mechanism with Bcl-2 as a mediator of the effects of miRNA-10b upon medulloblastoma cell survival." (PMID 26394044, 2015). "BCL2 expression was assessed in the same group of 8 medulloblastoma cell lines which had been previously assessed for the expression of miRNA-10b and it was found that the cell lines with high levels of miRNA-10b expression also had high levels of Bcl2 expression." (PMID 26394044, 2015). "Moreover, curcumin was also effective at improving the cytotoxic effects induced by cisplatin and γ-rays via the down-regulation of the anti-apoptotic factor Bcl-2 in medulloblastoma cells." (PMID 21859497, 2011). "In addition, OTX2-AS1 expression may serve as a molecular biomarker to indicate the vulnerability of medulloblastoma cells toward pharmacological inhibition of BCL-2." (PMID 37976029, 2023). "Thus, combining BCL-2 inhibitors with standard therapies for medulloblastoma may achieve synergistic effects for improved therapeutic response." (PMID 37976029, 2023). "Therefore, by assessing the mitochondria-derived factors mediating the cell death process we successfully demonstrated that inhibition of uPAR and MMP-9 decreased the expression of Bcl-2 and Bcl-xL, activated Bid cleavage, and enhanced Bak expression in medulloblastoma cells." (PMID 22984561, 2012). "Medulloblastoma-associated CSCs selected by serum-free medium with bFGF and EGF can form 3 D spheroids and display enhanced self-renewal and highly co-expressed stem cell genes (Oct4, Nanog, Nestin, and Musashi-1) as well as anti-apoptotic genes (Bcl-2 and Bcl-XL)." (PMID 20718984, 2010). "And as seen from the changes of increased cleaved PARP, activity of caspase-3 and decreased Bcl-2 expression with the increased dose of BDDD-721, BDDD-721 activated the mitochondria apoptotic pathways in medulloblastoma cells." (PMID 35802536, 2022). "miRNA-10b inhibition could also decrease the expression of BCL2 and MCL-1 protein expression in medulloblastoma cell lines." (PMID 35111757, 2021).
medulloblastoma (continued). "The expression of Bcl2 and Caspase3 in the VASH2-OE group was the most significant difference compared to the other two groups (P < 0.05), and the results showed that VASH2 may be a key factor affecting apoptosis in SHH medulloblastoma cell-lines DAOY." (PMID 37821528, 2023). "Because some cancer prognostic factors such as VEGF, Bcl-2 and survivin are the downstream genes of STAT3 signaling, the constitutive STAT3 activation may lead to unfavorable outcomes for the large-cell and classic medulloblastomas." (PMID 28035977, 2016). "This is further supported by the fact that two medulloblastoma cell lines with no endogenous expression of miRNA-10b also have no BCL2 expression, suggesting that high levels of miRNA-10b increase BCL2 levels, thereby increasing the proliferation and survival of medulloblastoma cells." (PMID 26394044, 2015). "It has been noticed that the curcumin-resistant medulloblastoma cells, which exhibited no decrease in the levels of SHH and Bcl-2 levels could be sensitized to curcumin by a co-treatment with SMO antagonist, cyclopamine." (PMID 21859497, 2011). "The results showed that Smad2 + 3, Smad4, Bcl2, and Caspase3 expression was changed in SHH medulloblastoma cell lines DAOY regardless of overexpression or knockdown of VASH2, indicating that VASH2 expression in myeloblasts may be mediated by affecting downstream indicators of TGFβ pathway." (PMID 37821528, 2023).
sarcoma (32 papers, 2010 to 2025). A usually aggressive malignant neoplasm of the soft tissue or bone. "There are sarcomas that are usually associated with Bcl-2 expression, namely on immunohistochemistry." (PMID 37720343, 2023). "Bcl‐2 causes chemoresistance in sarcoma, and chemosensitivity to doxorubicin and cisplatin can be restored by the Bcl‐2 inhibitor ABT‐737." (PMID 28145098, 2017). "Anoikis resistance in sarcomas has been described to be associated with integrins, Bcl-2 and caspase-8, CD99 isoforms, RANK, and ERK." (PMID 25905041, 2015). "The neuroendocrine tumor was positive for chromogranin and synaptophysin; GIST showed immunopositivity for CD117 and SMA; Synovial sarcoma showed immunoexpression of panCK, Bcl2 and TLE1; and epithelioid angiomyolipoma was positive for vimentin, CK7 and HMB45." (PMID 38235567, 2024). "In this review, there is a focus on the Bcl-2 functions in cancer, with an emphasis on sarcomas, and their role in precision therapy, mainly of the Bcl-2 homology 3 (BH3)-mimetics/Bcl-2 inhibitors." (PMID 37720343, 2023). "As expected, the SS tumors had a high expression of BCL2 across all samples which, as a group, was significantly higher than any other sarcoma group." (PMID 34065859, 2021). "Compared to the atypical sarcoma, all cell lines expressing the fusion protein showed elevated expression levels of BCL-2." (PMID 34065859, 2021). "The reduced sarcoma growth in the CTX + MAA group was accompanied by enhancement of Bax/Bcl-2/Caspase 3 mediated apoptosis, and inhibition of Beclin-1/LC-3 II mediated autophagy." (PMID 27043621, 2016). "Bcl-2 protein expression has been described as a characteristic marker of SS and is useful for its differentiation from other sarcomas." (PMID 21157548, 2010). "Tumor histology may show a similar appearance to PSS, so to differentiate PSS from other sarcomas, the immunohistochemistry for vimentin, BCL-2, CD99, and TLE1 are common positive markers." (PMID 37170363, 2023). "This high concentration of ROS observed in sarcoma 180 may be related to a more dynamic facility to express BCL-2 to relieve oxidative stress in cases of free radical elevation." (PMID 34961767, 2021). "A heatmap of all these genes involved in cell fate determination revealed various changes in their mRNA levels when ATF4 was overexpressed, with the most distinct downregulation of BCL2, one prominent gene that is highly expressed in bone-related sarcoma samples." (PMID 31534554, 2019). "A few indicators, including bcl-2 and CD117, have been identified as sarcoma-specific chromosomal abnormalities and have increased molecular adjunction in MPT." (PMID 37635229, 2023). "Of note, CIC-DUX4 translocation sarcomas have been reported to show WT1 staining in >90%, while BCOR-translocation sarcomas were reported to show strong staining of BCOR, BCL-2, cyclinD1, and TLE1 staining in most cases (each 80–90%)." (PMID 32204536, 2020). "PPSS expresses tumor markers such as transducin-like enhancer of split-1 (TLE1) and B-cell lymphoma 2 (Bcl-2), which can differentiate PPSS from other sarcomas, highlighting the importance of immunohistochemical (IHC) investigations as an important tool to rule out other sarcomas." (PMID 40718269, 2025). "In our study, the ratio of Bcl-2/Bax was reduced in sarcoma cells treated in vitro with the combination of LFU and PTX, suggesting that the combination of LFU and PTX enhances apoptosis in sarcoma cells." (PMID 36582521, 2022).
sarcoma (continued). "The 33 novel fusions were identified in 21 patients involving RB1, BCL2, and BRCA2; none were identified in patients with TRS, and 21 (21.0%) were identified in patients with genomically complex and other sarcomas (p < 0.001)." (PMID 40755265, 2025). "Biopsy of renal mass revealed poorly differentiated sarcoma and IHC was positive for vimentin, CD99, and BCL2 and negative for AE1, epithelial membrane antigen, and leukocyte common antigen." (PMID 25610686, 2014). "In addition, 33 novel gene fusions involving RB1, BCL2, and BRCA2 were identified in 21 patients, predominantly in genomically complex and other sarcomas, not in TRS." (PMID 40755265, 2025).